KRAS (KRas proto-oncogene, GTPase)
Diseases named in the same sentence as KRAS in open-access papers (continued):
Sharing a sentence is not in itself a finding about the gene and the disease.
colorectal cancer (continued). "In this respect, the most common somatic mutations of Kirsten Rat Sarcoma Viral Oncogene Homolog KRAS and BRAF oncogenes are known to play an important role in the advance and progression of both colorectal cancer (CRC) and melanoma." (PMID 30935124, 2019). "Our findings provide a novel explanation for the limited response to MEK inhibitors in KRAS-mutant colorectal cancer, known for its inflammatory nature." (PMID 30353166, 2019). "In this study we show that the APC and KRAS mutant human colorectal cancer cell line HCT-15 induces canonical WNT signaling through YAP in a MEK dependent mechanism." (PMID 30717152, 2019). "In colorectal cancer, Kirsten-RAS (KRAS) and neuroblastoma-RAS (NRAS) are the commonly mutated isoforms." (PMID 31816869, 2019). "By regulating the Ago2 secretion, GTPase KRas (KRAS) has been involved in the miRNA compartmentalization into EVs released by colorectal cancer cells." (PMID 31247906, 2019). "The “Cetuximab After Progression in KRAS wild-type colorectal cancer patients” (CAPRI) study enrolled KRAS exon 2 wt mCRC patients who received first-line FOLFIRI plus cetuximab, and at progression were randomized to FOLFOX alone or FOLFOX plus cetuximab." (PMID 31226844, 2019). "A recent report of ours clarified the efficient anti-tumor effect of syn-miR-143 on colorectal cancer cells, which occurred by impairing the KRAS networks systematically; and similar effects of syn-miR-143 were presently shown even in HER2-positive GC cells." (PMID 30959742, 2019). "A majority of KRAS-positive colorectal cancers (CRCs) have a CpG island methylator phenotype (CIMP)." (PMID 31635338, 2019). "KRAS, BRAF and PIK3CA were also presented as screen factors in colorectal cancers using their mutations." (PMID 31263147, 2019). "Previous studies have demonstrated that receptor tyrosine kinases exert dominant control over PI3K signaling in human KRAS-mutant colorectal cancers." (PMID 31164794, 2019). "Both KRAS wild-type and mutant cohorts of colorectal cancer patients were shown to exhibit high DDX3X expression associated with poor overall survival and relapse-free survival." (PMID 31906196, 2019). "In this study, we estimated the performance of BNA-clamp PCR with Sanger sequencing method to detect KRAS, NRAS and BRAF mutations in colorectal cancers and compared the results from PCR-rSSO and NGS." (PMID 31711486, 2019). "In colorectal cancer, APC loss-of-function mutations synergize with KRAS-activating mutations to activate cancer stem cells." (PMID 31213486, 2019). "Second, shRNA knockdown or CRISPR/Cas9 KO of ORP5 or ORP8 mislocalized PtdSer and KRAS from the PM and decreased the extent of KRAS PM clustering in human pancreatic, breast and colorectal cancer cells." (PMID 31451509, 2019). "KRAS mutations are frequent in PDAC, lung, and colorectal cancers, and also occur in other cancers such as multiple myeloma." (PMID 31681587, 2019). "A work on colorectal cancer cells showed that the exosomal loading mechanism is a KRAS-dependent and KRAS-mutant cells abundantly release miRNA-100 while normal KRAS cells sort a high volume of miRNA-100 to the exosomes lumens incorporation with nSMAse." (PMID 31291956, 2019). "Only a small fraction of EGFR positive cancers represented by advanced colorectal cancers expressing wild type KRAS respond to anti-EGFR mAbs although acquired resistance also commonly occurs." (PMID 31508364, 2019). "Evidence of antitumour activity was observed at doses as low as 48 mg, including prolonged SD with target lesion reduction (−24%) in a patient with KRAS mutant colorectal cancer." (PMID 31303643, 2019).
colorectal cancer (continued). "Multiple studies have consistently demonstrated the critical role of KRAS in the overwhelming majority of pancreatic cancers and many colorectal cancers." (PMID 31413817, 2019). "Nimotuzumab-PEG6-DM1-Low and nimotuzumab-PEG6-DM1-High were used to treat EGFR positive KRAS mutant DLD-1 colorectal cancer xenograft." (PMID 30800216, 2019). "NFκB is considered a crucial component of drug resistance in mutant KRAS driven tumors such as pancreatic cancer and colorectal cancer, which typically expresses high levels of the protein." (PMID 31681587, 2019). "BRAFV600E mutant colorectal cancers have been shown to express differential activation of the KRAS/AKT pathway and cell cycle proteins, indicating a diverse biology for a subtype of colorectal cancers even driven by the same driver mutation." (PMID 30925167, 2019). "Proliferation and survival related signaling pathways such as PI3K/AKT/mTOR and RAS/RAF/MEK/ERK play important roles in pathogeneses of solid tumors, and KRAS, BRAF, and PIK3CA (PI3K) mutations are the most common in colorectal cancer." (PMID 31624493, 2019). "Overall, we confirmed the clinical utility of BNA-clamp PCR for detecting KRAS, NRAS and BRAF mutations in colorectal cancers." (PMID 31711486, 2019). "Recently one of the orthotopic models has been extended and refined into a sophisticated GEMM-derived orthotopic transplant model of KRAS-mutant colorectal cancer for high-throughput drug discovery screening and candidate drug validation." (PMID 31766149, 2019). "TKIs are approved for NSCLC especially for cancers expressing mutated EGFR, whereas anti-EGFR mAbs are approved for KRAS wild-type colorectal cancer and local regional head and neck cancers." (PMID 31508364, 2019). "The mutations of KRAS and BRAF oncogenes are involved in colorectal cancer and melanoma, while the NRAS mutations are associated with melanoma." (PMID 30935124, 2019). "BCAM was reported to mediate recognition between tumor cells and the endothelium in KRAS-Mutant colorectal cancer." (PMID 32063918, 2019). "We first examined the mutation status of the KRAS, PIK3CA and BRAF genes in human colorectal cancer cell lines." (PMID 31769426, 2019). "Among colorectal carcinoma cell lines, only HCT116 cells with inherent KRAS mutation are known to show anoikis resistance." (PMID 31545494, 2019). "MAPK signaling activity confers inherent radioresistance to KRAS-mutant colorectal carcinoma cells by rapidly upregulating of heterogeneous nuclear ribonucleoprotein K (hnRNPK)." (PMID 31138194, 2019). "Similar to KRAS, BRAF is a well-known proto-oncogene and the p.V600E mutation is implicated in a number of cancers including melanoma, colorectal carcinoma, and papillary thyroid carcinoma." (PMID 31891627, 2019). "Genetic alterations in the MAPK pathway (including the mutation of KRAS, NRAS and BRAF genes) can cooperate in the development of B16 melanomas and CT26 colorectal carcinoma." (PMID 30935124, 2019). "Non-small cell lung cancer cells with KRAS or EGFR mutations and colorectal carcinoma cells also show the dichotomy of AKT1 during tumor progression and metastasis." (PMID 31752925, 2019). "KRAS and BRAF mutations are common in colorectal cancer and are associated with upregulation of GLUT1 and a glycolytic phenotype." (PMID 30018566, 2018). "KRAS-driven colorectal cancer is initiated from the epidermal growth factor (EGF) binding to the EGF receptor (EGFR), which activates GTP-bound KRAS." (PMID 30577618, 2018). "To achieve this, we generated a unique antagonist monoclonal antibody (D-A10 MAb) targeting an eight-amino-acid-long domain of eK8, which enabled us to ascertain the pro-tumoral activity of eK8 in both KRAS-mutant and wild-type colorectal cancers (CRC)." (PMID 30453567, 2018). "Recent evidence showed how combined analysis of KRAS and PIK3CA mutations, MET and PTEN expression in primary tumors and corresponding metastases in colorectal cancer demonstrated discordance between the two sites." (PMID 30282914, 2018).
colorectal cancer (continued). "In colorectal cancer, ESP subtypes were correlated with KRAS and BRAF mutation status and also separated primary colon from primary rectal tumors." (PMID 30297789, 2018). "One example are human colorectal cancer HCT-116 cells, which harbor a heterozygous KRAS G13D mutation." (PMID 29662661, 2018). "To further demonstrate the potential of the present palmtop bioanalyzer in real sample analysis, we applied it in the separation of PCR products and RFLP digestion products of KRAS proto-oncogene for actual colorectal cancer (CRC) diagnosis." (PMID 29379053, 2018). "Colorectal cancer cells frequently become addicted to oncogenic signals such as KRAS, which has led researchers to try to develop therapies that target them." (PMID 29907857, 2018). "Myc-positive neuroblastoma, KRAS-positive colorectal cancer and multiple myeloma cells showed marked cell growth inhibition in response to HDAC6 inhibitors." (PMID 30318510, 2018). "miR-1298 has been identified in a global miRNA functional screen as selectively lethal to cells expressing mutated KRAS, which is an oncogene mutated in 20% of human cancers, mainly NSCLC and colorectal cancers." (PMID 29891810, 2018). "Examples of this include the use of trastuzumab following HER2 testing in breast cancer, use of endocrine therapy in breast cancer and guiding EGFR targeted therapies in colorectal cancer using KRAS testing." (PMID 30234014, 2018). "Here, C19 has superior effects on the inhibition of viability, proliferative capacity and induction of apoptosis in KRAS-dependent colorectal cancer cells." (PMID 30382908, 2018). "Although MEK blockade has been highlighted as a promising antitumor drug, it has poor clinical efficacy in KRAS mutant colorectal cancer (CRC)." (PMID 29896883, 2018). "Mutations in KRAS exon 2, BRAF and PIK3CA are commonly present in colorectal cancer (CRC) worldwide, but few data about RAS mutations outside KRAS exon 2 are available for Chinese CRCs." (PMID 29666387, 2018). "The gain-of-function KRAS mutations, in particular, are responsible for bypassing EGFR upstream signals resulting in poor response to anti-EGFR therapies in 30–40% of colorectal cancer." (PMID 29304017, 2018). "The study by Lan and coworkers showed a higher frequency of MSI, KRAS and PI3KCA mutations in proximal than in distal colorectal cancers." (PMID 29652830, 2018). "In KRAS mutant colorectal cancer cell lines, genetic ablation of the human ortholog of IRE1, ERN1, does not affect growth but sensitizes to MEK inhibition." (PMID 30482246, 2018). "The KRAS oncogene is involved in the pathogenesis of several types of cancer, particularly colorectal cancer (CRC)." (PMID 29304017, 2018). "Overexpression of LAMA5 can induce colorectal cancer through KRAS, while the genetic inactivation of LAMA5 impairs the adhesion of KRAS-mutant colorectal cancer cells." (PMID 29883365, 2018).
colorectal cancer (continued). "Examples include testing for epidermal growth factor receptor (EGFR) to determine the use of erlotinib in advanced nonsmall cell lung cancer (NSCLC), and KRAS testing to determine the use of cetuximab in advanced colorectal cancer." (PMID 29772692, 2018). "Our results provide the basis for a rational combination strategy against KRAS mutant colorectal cancers, predicated on the understanding of cross talk between the MEK and MIF pathways." (PMID 29896883, 2018). "In conclusion, GSC suppressed KRAS-driven colorectal cancer growth both in vitro and in vivo, and can be used as an alternative or simultaneous approach in colorectal cancer therapy." (PMID 30577618, 2018). "In colorectal cancer (CRC), mutations of EGFR downstream targets occur especially in the GTPase KRAS in up to 45% and in the phosphatidylinositol-4,5-bisphosphate 3-kinase, catalytic subunit alpha (PIK3CA) in up to 30% of patients." (PMID 30001368, 2018). "PI3KCA mutation in colorectal cancer is associated with phosphorylated AKT expression, CTNNB1 inactive status and KRAS mutations." (PMID 29652830, 2018). "For example, Bardelli and colleagues have demonstrated that KRAS mutant sub-clones of colorectal cancers are more sensitive to withdrawal of an EGFR monoclonal antibody-based regimen such as cetuximab than are their wildtype counterparts." (PMID 29491834, 2018). "This platform identified KRAS and BRAF hot‐spot mutations following cfDNA isolation from the blood plasma and tissues obtained from 30 colorectal cancer patients." (PMID 30356899, 2018). "A comparative study for PFS and OS of the WT and MT KRAS colorectal cancer patients has been done with antibody therapy (panitumumab, cetuximab and bevacizumab) alone along with the combination of antibody and chemotherapy (FOLFOX-4)." (PMID 29484148, 2018). "In an extended analysis of 1732 QUASAR 2 and Australian colorectal cancers for which KRAS, BRAF, and MSI status were available, KRAS and BRAF mutations were specifically associated with poor prognosis in MSI-negative cancers." (PMID 30042065, 2018). "The aim of FOCUS4-D was to test the efficacy of AZD8931 in patients with colorectal cancer whose tumours are wild-type for BRAF, PIK3CA, KRAS, and NRAS mutations." (PMID 29254887, 2018). "Here, we assessed the efficacy of EGFR mAbs in simultaneous and sequential combinations with oxaliplatin in a panel of colorectal cancer cell lines with different genetic backgrounds (wild-type or mutant for KRAS or BRAF)." (PMID 30410004, 2018). "Despite rapid advances in high-throughput screening technologies, only a handful of predictive biomarkers are routinely tested in TB to guide treatment decisions (e.g., EGFR in non-small cell lung cancer or KRAS in colorectal cancer)." (PMID 29544535, 2018). "Since the discovery that BRAF and KRAS are oncogenic drivers of colorectal cancer, much progress has been made in understanding their common and individual effects." (PMID 29907857, 2018). "Mutations in genes in both pathways, such as adenomatous polyposis coli (APC) and KRAS, which occur in as many as 90% and in 40–50%1,2, respectively, of human colorectal cancers (CRCs), are known to be involved in the initiation and progression of CRC." (PMID 30459318, 2018). "Present study found the epigenetic modifications of histones near the splicing sites affected the ratio of KRAS-4A vs. KRAS-4B by the differential AS patterns in colorectal cancer cell lines." (PMID 30524964, 2018).
colorectal cancer (continued). "As a result, GSC suppressed cell proliferation by inducing the apoptosis of KRAS-driven colorectal cancer cells and inhibited clonogenic capabilities." (PMID 30577618, 2018). "Here, we provide experimental evidence that C19 selectively inhibits the viability of KRAS-dependent colorectal cancer cells." (PMID 30382908, 2018). "KRAS/NRAS mutations are therapeutically relevant for melanomas, colorectal cancer, and thyroid cancer (OncoKB level 3)." (PMID 30442178, 2018). "Loss of function of let-7a was associated with high levels of KRAS and c-MYC and colon tumorigenesis, while the let-7 KRAS rs712 polymorphism was correlated with increased colorectal cancer risk." (PMID 30469518, 2018). "We have successfully replicated our previous results demonstrating an association between FCGR2A genotype and survival in wild‐type KRAS colorectal cancer patients treated with cetuximab." (PMID 30318772, 2018). "We used the BRAF and KRAS wildtype CaCO2 colorectal carcinoma cell line, harboring Doxycycline inducible constructs expressing BRAFV600E and KRASG12V as well as cell lines with naturally occurring BRAFV600E (HT29) and KRASG12V (SW480) mutations." (PMID 29907857, 2018). "The Ras pathway genes KRAS, BRAF, or ERBBs have somatic mutations in ~ 60% of human colorectal carcinomas." (PMID 29301589, 2018). "A study showed that baseline MAPK signaling activity conferred intrinsic radioresistance to KRAS-mutant colorectal carcinoma cells by rapid up-regulation of hnRNP K." (PMID 29922514, 2018). "We first analyzed the mutational status of KRAS and BRAF in colorectal cancers from our cohort of patients." (PMID 29115941, 2017). "Based upon this data, a phase I study of MEK inhibition with cobimetinib and PD-L1 inhibition with atezolizumab (MPDL3280A, Tecentriq) was undertaken with an expansion cohort in KRAS mutant colorectal cancer." (PMID 28492495, 2017). "Both BRAF and KRAS oncogenes encode proteins involved in the MAPK pathway, and BRAF mutation has been reported to be mutually exclusive with KRAS mutation in colorectal cancer." (PMID 28623901, 2017). "For example, in colorectal cancer, BRAF mutations are mutually exclusive with mutations in KRAS, indicating that a single alteration of the activity of a pathway member is sufficient to induce misregulation of that pathway." (PMID 28333948, 2017). "This pilot study involving 12 patients exploring intra-tumour heterogeneity of colorectal cancer has demonstrated relative homogeneity of genetic factors (BRAF and KRAS mutations), as well as epigenetic homogeneity (in terms of DNA methylation)." (PMID 28097409, 2017). "In colorectal cancer patients, AREG expression in particular has been repeatedly associated with an enhanced responsiveness to cetuximab, especially for KRAS wild-type tumours." (PMID 27933395, 2017). "The results from this work suggest that the majority of colorectal cancers are largely homogenous in terms of KRAS, BRAF and CIMP status." (PMID 28097409, 2017). "In a KRAS-mutant CT26 mouse colorectal cancer model, the impact on the tumor microenvironment (TME) and the spleen were evaluated by flow cytometry." (PMID 28807001, 2017). "The authors suggest that combination therapies of ADAM17 and c-MET inhibitors would be more clinically effective in KRAS mutant colorectal cancer." (PMID 29230082, 2017). "Data on the HRs for death in KRAS wild type colorectal cancer patients with liver-confined metastases were available in 3 RCTs (326 patients)." (PMID 28167959, 2017). "On the other hands, both mutations in KRAS and BRAF have been clearly demonstrated to predict resistance to EGFR-directed therapy in colorectal cancer." (PMID 29312543, 2017). "Of course, the differences of HER2 status and hormone receptor status in breast cancer, lesion sites and KRAS status in colorectal cancer, make the related subgroup analysis very challenging." (PMID 28978022, 2017).